CACNA1E (calcium voltage-gated channel subunit alpha1 E)
Description:
Voltage-sensitive calcium channels (VSCC) mediate the entry of calcium ions into excitable cells. They are also involved in a variety of calcium-dependent processes, including muscle contraction, hormone or neurotransmitter release, gene expression, cell motility, cell division and cell death. The isoform alpha-1E gives rise to R-type calcium currents. R-type calcium channels belong to the 'high-voltage activated' (HVA) group and are blocked by nickel. They are however insensitive to dihydropyridines (DHP). Calcium channels containing alpha-1E subunit could be involved in the modulation of firing patterns of neurons which is important for information processing. [Isoform 3]: Voltage-sensitive calcium channels (VSCC) mediate the entry of calcium ions into excitable cells. They are also involved in a variety of calcium-dependent processes, including muscle contraction, hormone or neurotransmitter release, gene expression, cell motility, cell division and cell death. The isoform alpha-1E gives rise to R-type calcium currents.
Synonyms: BII; CACH6; CACNL1A6; Cav2.3; DEE69; EIEE69; gm139
Tractability: Small molecule: an approved drug acts on it; a structure with a bound ligand is known; a high-quality ligand is known; it belongs to a druggable protein family. Antibody: its Gene Ontology location is reachable by antibodies, with high confidence; UniProt predicts a signal peptide or a membrane-spanning region; the Human Protein Atlas places it where antibodies can reach. PROTAC: ubiquitination databases record sites on it; its protein half-life has been measured.
Target class: Voltage-gated calcium channel; Ion channel; Voltage-gated ion channel
Gene: Protein-coding gene on chromosome 1 (181,317,690 to 181,813,262, forward strand). Ensembl gene ENSG00000198216.
Subcellular location: Membrane
Subcellular location (Human Protein Atlas): Plasma membrane; Actin filaments; Cytosol
Pathways (Reactome):
Metabolism: Regulation of insulin secretion
Neuronal System: Presynaptic depolarization and calcium channel opening
Gene Ontology:
Molecular function: voltage-gated calcium channel activity; voltage-gated monoatomic cation channel activity; high voltage-gated calcium channel activity; calcium ion binding; monoatomic ion channel activity
Biological process: calcium ion import across plasma membrane; chemical synaptic transmission; calcium ion transmembrane transport; monoatomic ion transport; transmembrane transport
Cellular component: neuronal cell body; plasma membrane; voltage-gated calcium channel complex; membrane; synapse
Genetic constraint (gnomAD): Loss-of-function variants: 27 observed, 168.83 expected, observed/expected ratio (o/e) 0.16, 90% interval 0.12 to 0.22. The upper end of that interval is the gene's LOEUF score, 0.22, which puts it in group 1 of 6, group 1 being the genes least tolerant of losing a copy. Missense variants: 1,553 observed, 2,466.5 expected, observed/expected ratio (o/e) 0.63, 90% interval 0.6 to 0.66. Synonymous variants: 899 observed, 941.96 expected, observed/expected ratio (o/e) 0.95, 90% interval 0.9 to 1.01.
Gene-disease validity (ClinGen):
ClinGen rates the evidence that CACNA1E causes each of these diseases.
genetic developmental and epileptic encephalopathy (autosomal dominant): Definitive. A complex neurodevelopmental disorder characterized by a range of developmental delays and epileptic encephalopathy phenotypes.
Homologues: Orthologues: chimpanzee CACNA1E (100% identical), macaque CACNA1E (97% identical), pig CACNA1E (97% identical), guinea pig CACNA1E (96% identical), mouse Cacna1e (95% identical), rat Cacna1e (95% identical), dog CACNA1E (94% identical), tropical clawed frog cacna1e (77% identical), zebrafish cacna1eb (59% identical), zebrafish cacna1ea (48% identical). Paralogues in human: CACNA1A (59% identical), CACNA1B (56% identical), CACNA1C (34% identical), CACNA1D (34% identical), CACNA1S (33% identical), CACNA1F (32% identical), CACNA1I (22% identical), CACNA1G (21% identical), CACNA1H (21% identical), SCN2A (21% identical), SCN3A (21% identical), SCN8A (21% identical), and 14 more.
Diseases named in the same sentence as CACNA1E in open-access papers:
CACNA1E is named in the same sentence as 84 diseases in open-access papers, as found by Europe PMC text mining. Sharing a sentence is not in itself a finding about the gene and the disease. The quoted sentences say what the papers report.
epilepsy (12 papers, 2019 to 2026). A brain disorder characterized by episodes of abnormally increased neuronal discharge resulting in transient episodes of sensory or motor neurological dysfunction, or psychic dysfunction. "A large multiplex gene network analysis identified CACNA1E as candidate gene for epilepsy and autism." (PMID 34702355, 2021). "One large genomic study of trios presenting with NDD identified CACNA1E as a candidate gene for NDD with or without epilepsy, and subsequently, variants in CACNA1E have been found in patients with developmental and epileptic encephalopathy (DEE)." (PMID 34702355, 2021). "This review delves into the significance of the CACNA genes, including CACNA1A, CACNA1B, CACNA1C, CACNA1D, CACNA1E, CACNA1G, and CACNA1H, in the pathogenesis of conditions such as migraine, epilepsy, cerebellar ataxia, dystonia, and cerebellar atrophy." (PMID 38785745, 2024). "The present work adds CACNA1E to the expanding list of genes implicated in an autosomal dominant neurodevelopmental disorder, including ASD, with or without epilepsy." (PMID 34702355, 2021). "Finally, we use our analysis to prioritize new candidate genes for epilepsy (i.e. ANK2, CACNA1E, CACNA2D3, GRIA2, DLG4) for further validation." (PMID 33441621, 2021). "Additionally, four of the brain-expressed, constrained genes that we identified through the new paralog conservation test and presented in the first pre-print version of the manuscript, CHD3, CACNA1E, PHIP, and GABRB2, were recently shown to be significantly enriched in NDDs with epilepsy." (PMID 32183904, 2020).
Epileptic encephalopathy (9 papers, 2020 to 2026). A condition in which epileptiform abnormalities are believed to contribute to the progressive disturbance in cerebral function. "De novo variants in CACNA1E, the gene encoding the Cav2.3 voltage-gated calcium channel, are often associated with severe neurodevelopmental disorders, including developmental and epileptic encephalopathy." (PMID 42123681, 2026). "Here the authors show that a model of CDKL5 deficiency disorder involves a channelopathy of CACNA1E gain-of-function, molecularly linking two distinct single-gene developmental and epileptic encephalopathies." (PMID 38081835, 2023). "The association between CACNA1E variants and developmental and epileptic encephalopathy was published subsequent to the completion of the patient’s original exome and reported on reanalysis." (PMID 35937981, 2022). "De novo variants in the voltage-gated calcium channel subunit α1 E gene (CACNA1E) have been described as causative of epileptic encephalopathy with contractures, macrocephaly and dyskinesias." (PMID 34702355, 2021). "Our results indicate that developmental and epileptic encephalopathies caused by CDKL5 and CACNA1E are related at the molecular level." (PMID 38081835, 2023). "Both CACNA1E and KCNQ2 are clinically relevant genes associated with epileptic encephalopathy." (PMID 38283851, 2024). "The initial diagnostic test was performed, and CACNA1E encoding a subunit of a calcium channel was considered a candidate for epileptic encephalopathy; however, the OMIM database did not clearly report this gene and the related disease." (PMID 32695065, 2020). "Thus, our results establish Cav2.3 overactivity as a common feature of CACNA1E (DEE69) and CDKL5 (DEE2) epileptic encephalopathies, potentially explaining some of the overlapping clinical features of these diseases." (PMID 38081835, 2023).
Parkinson disease (6 papers, 2019 to 2024). A progressive degenerative disorder of the central nervous system characterized by loss of dopamine producing neurons in the substantia nigra and the presence of Lewy bodies in the substantia nigra and locus coeruleus. "The investigation of the role of the cacna1e gene in a neurotoxin Parkinson’s mouse model revealed that the Cav2.3 knockout even reduced activity-associated nigral somatic Ca2+ signals and Ca2+-dependent afterhyperpolarizations, leading to full protection from degeneration in vivo [2a]." (PMID 33009476, 2020). "Our results are consistent with the findings presented herein, providing evidence that GPR 78 and CACNA1E have the potential to serve as a valuable biomarker for facilitating the diagnosis of Parkinson’s disease." (PMID 38882525, 2024). "Our study reported co-DEGs of GPR78, CADM3, and CACNA1E link NETs and Parkinson’s disease and established a nomogram model to diagnose PD based on these genes, which also performed well in external cohort validation." (PMID 38882525, 2024).
diabetes (5 papers, 2012 to 2024). "First, as already shown by us for TCF7L2 and GCKR, a role of CACNA1E in determining beta cell function can be detected also in overt diabetes." (PMID 22427875, 2012). "This is the first study to analyse the sequence of the MTOR, TBC1D4, CACNA1E, SLC19A2 and KCNH6 genes in Polish patients with suspected MODY-X diabetes using the NGS method." (PMID 38932873, 2024).
type 2 diabetes (5 papers, 2009 to 2024). "Through this approach, we identified DRD3 and CACNA1E to be potential targets for the treatment of type 2 diabetes." (PMID 30131871, 2018). "Genetic variability of the major subunit (CACNA1E) of the voltage-dependent Ca2+ channel CaV2.3 is associated to risk of type 2 diabetes, insulin resistance and impaired insulin secretion in nondiabetic subjects." (PMID 22427875, 2012).
autism (4 papers, 2015 to 2023). Persistent deficits in social interaction and communication and interaction as well as a markedly restricted repertoire of activity and interest as well as repetitive patterns of behavior. "Moreover, a whole exome resequencing study identified rare de novo alleles of CACNA1D and CACNA1E as "top de novo risk mutations" for autism." (PMID 26566276, 2015).
migraine (4 papers, 2007 to 2025). "Beyond CACNA1A, other genes within the CACNA family, such as CACNA1B (encoding CaV2.2) and CACNA1E (encoding CaV2.3), have also been implicated in the pathogenesis of migraine aura." (PMID 39997646, 2025). "Six markers localised to the C1q23-C1q31 region covering several genes of interest (ATP1A4, CASQ1, KCNJ9 and J10, FasL and CACNA1E), have been analysed in regard to their potential association with migraine in a large population (243 migraineurs versus 243 healthy individuals)." (PMID 17727731, 2007). "There are three studies that reported the association of single-nucleotide polymorphisms in the Cav2.3 gene (CACNA1E) with postoperative pain and opioid consumption as well as with the prevalence of migraine in patients." (PMID 37581322, 2024). "Several genes have been studied including membrane protein (ATP 1 subtype A4 and FasL), cytoplasmic glycoprotein (CASQ 1) genes and potassium (KCN J9 and KCN J10) and calcium (CACNA1E) channel genes in 243 migraineurs (including 85% MA and 15% of migraine without aura (MO)) and 243 matched controls." (PMID 17727731, 2007).
bipolar disorder (3 papers, 2018 to 2023). A disorder of the brain that causes unusual shifts in mood, energy, activity levels and the ability to carry out day-to-day tasks. "The CACNA1E gene has been shown to be associated with bipolar disorder." (PMID 30034349, 2018).
breast carcinoma (3 papers, 2018 to 2023). "Significant differences in the validation set of samples were found for seven genes; the combination of the four genes GCM2, ITPRIPL1, CACNA1E, DLGAP2 (AUC = 0.99) showed the highest diagnostic value based on logistic regression for all breast cancer samples." (PMID 37628841, 2023). "Previous findings showed that CACNA2D2 promote tumorigenesis by stimulating cell proliferation and angiogenesis in prostate and breast cancer while CACNA1E was upregulated in lung squamous cell carcinoma and wilms tumor." (PMID 34299042, 2021). "CACNA1E, calcium voltage-gated channel subunit alpha-1 E, was shown to be underexpressed in breast cancer compared with normal tissue and was hypothesized to be a tumor suppressor gene in some types of cancer." (PMID 29854292, 2018).
developmental and epileptic encephalopathy (3 papers, 2021 to 2022). An epilepsy associated with developmental impairment that may be due to either the underlying etiology or the superimposed epileptic activity, or both. "Thirteen genes were found disrupted, in which the CACNA1E (in case 12) and STARD7 (in case 17) genes are associated with the developmental and epileptic encephalopathy (MIM: #618285) and the familial adult myoclonic epilepsy (MIM: #607876), respectively." (PMID 36186435, 2022). "Mutations in the CACNA1E cause developmental and epileptic encephalopathy (DEE; OMIM 618285), a severe and genetically heterogeneous neurodevelopmental disorder characterized by characterized by refractory infantile-onset seizures, severe hypotonia, and profound developmental impairment." (PMID 33983923, 2021).
developmental delay (3 papers, 2021 to 2025). "DEE69, caused by gain-of-function mutations in the CACNA1E-encoded voltage-gated calcium channel CaV2.3, is characterized by early-onset refractory seizures, profound developmental delay, movement disorders, congenital contractures (as seen in this patient), and visual abnormalities." (PMID 41492575, 2025).
Tinnitus (3 papers, 2022 to 2024). Tinnitus is an auditory perception that can be described as the experience of sound, in the ear or in the head, in the absence of external acoustic stimulation. "Meanwhile, other studies have shown that genes such as CACNA1E that influence the firing of neurons are also associated with tinnitus, which is applicable to our study, suggesting the altered excitability of neurons in the brain." (PMID 38562529, 2024). "The identification of genes such as CACNA1E or NAV2, showing enrichment of missense and large structural variants in patients with tinnitus may lead to defining new druggable targets for tinnitus." (PMID 38334885, 2024). "In this study, we report a burden of missense and LSV in constraint regions and support CACNA1E, NAV2, and TMEM132D as new candidate genes that contribute to severe tinnitus." (PMID 36450758, 2022).
Arrhythmia (2 papers, 2021 to 2023). Any cardiac rhythm other than the normal sinus rhythm. "CAMK2D, and CACNA1E, that are associated with abnormal calcium handling and arrhythmias respectively, were increased in multiple types of cardiac cells (e.g., CM, neuron, and fibroblast)." (PMID 37084237, 2023). "Furthermore, SLC9A1 and CACNA1E have been reported to regulate the development of other heart diseases, such as heart failure and arrhythmia." (PMID 33407844, 2021).
Developmental and Epileptic Encephalopathy-69 (2 papers, 2023 to 2025). "DEE69 (Developmental and Epileptic Encephalopathy-69; OMIM #618285), caused by pathogenic variants in the CACNA1E gene, is one such disorder that frequently presents with this specific phenotypic combination, including arthrogryposis-like contractures." (PMID 41492575, 2025).
fragile X syndrome (2 papers, 2019 to 2023). A genetic syndrome caused by mutations in the FMR1 gene which is responsible for the expression of the fragile X mental retardation 1 protein. "In addition to CDKL5 and CACNA1E encephalopathies, increased Ca2+ influx through Cav2.3 may contribute to seizures in Fragile X syndrome, as reduced FMRP function leads to increased Cav2.3 expression." (PMID 38081835, 2023).
Hypertension (2 papers, 2009 to 2017). The presence of chronic increased pressure in the systemic arterial system. "Genetic variants in CACNA1E are reported to play a role in hypertension." (PMID 28860667, 2017).
Intellectual disability (2 papers, 2021).
Atrophy (1 paper, 2022). Any weakening or degeneration, especially through lack of use. "More generally, genetic aberrations of many of the differentially methylated genes in our study, i.e., TRIO, NRXN2, SYN2, CACNA1E, DNM1 and RAB11B, have been associated with movement disorders, cognitive and visual impairments and brain abnormalities (e.g., atrophy, white matter apoplasia)." (PMID 35094644, 2022).
bladder cancer (1 paper, 2024). "These proteins include LTN1 (ovarian cancer), GBE1, CACNA1E and ADCY10 (lung cancers), as well as PLEKHS1 and ADNP (bladder cancer)." (PMID 38951817, 2024).
channelopathies (1 paper, 2026). "Our findings provide the first mechanistic evidence linking loss-of-function Cav2.3 pathogenic variants to variable neurological phenotypes, expanding the clinical spectrum of CACNA1E channelopathies." (PMID 42123681, 2026).
childhood kidney cancer (1 paper, 2020). "For example, CaV2.3 encoded by the human CACNA1E gene is upregulated in Wilm’s tumours (a rare childhood kidney cancer), and its expression level is associated with reduced relapse-free survival." (PMID 32575381, 2020).
concussion (1 paper, 2017). A concussion, also known as a mild traumatic brain injury (mTBI), is a head injury that temporarily affects brain functioning. "Taken together with the role of Cav2.3 in neurometabolic cascade, these findings suggest CACNA1E as a possible modulator of postconcussion stress response, in other words, concussion severity and duration." (PMID 30202567, 2017). "Although for the moment, no experimental data showing an association with concussion have been published, we speculate that CACNA1E could contribute to concussion incidence or outcome." (PMID 30202567, 2017). "Genetic polymorphisms in the genes contributing to plasticity and repair (APOE), synaptic connectivity (GRIN2A), calcium influx (CACNA1E), uptake and deposit of glutamate (SLC17A7) are potential biomarkers of concussion incidence and recovery rate." (PMID 30202567, 2017).
dengue (1 paper, 2020). "Several genes, e.g., NAMPT and CACNA1E, which were identified as the potential target genes of miR-320a in silico, were significantly downregulated under the severe dengue conditions." (PMID 32934118, 2020).
depression (1 paper, 2024). "In a microbiota-induced depression animal model, proteomic analysis of the olfactory bulb suggests CACNA1E and its downstream CREB signaling were down-regulated, which provides a novel insight for further research of the “microbiota-gut-brain axis”." (PMID 38882525, 2024).
epilepsy syndrome (1 paper, 2020). A syndrome that has a characteristic cluster of clinical features and/or lectroencephalographic (EEG) findings that reflect underlying epileptic activity. "Mutations in CACNA1E, SCN1B, and SCN9A were previously associated with various epilepsy syndromes." (PMID 32466254, 2020).
familial spastic paraplegia (1 paper, 2025). "The plasma membrane Ca2+ exporter encoded by ATP2B4 has been found mutated in familial spastic paraplegia, and voltage-dependent calcium channels comprising the CACNA1E-encoded subunit α1E have been linked to synaptic plasticity, as has been SYT17." (PMID 40019676, 2025).
glioblastoma (1 paper, 2022). The most malignant astrocytic tumor (WHO grade IV). "The genes DDN and SH3GL2 were found to be upregulated in the proneural subtype, while CACNA1E in the mesenchymal subtype of glioblastoma exhibits good prognostic potential." (PMID 35571016, 2022).